LCE1E (late cornified envelope 1E)
Description:
Precursors of the cornified envelope of the stratum corneum.
Synonyms: LEP5
Tractability: No criterion of Open Targets' tractability assessment is met for any kind of drug.
Gene: Protein-coding gene on chromosome 1 (152,786,214 to 152,788,426, forward strand). Ensembl gene ENSG00000186226.
Pathways (Reactome):
Developmental Biology: Formation of the cornified envelope
Gene Ontology:
Molecular function: identical protein binding; protein binding
Biological process: epidermis development
Genetic constraint (gnomAD): Loss-of-function variants: 4 observed, 5.26 expected, observed/expected ratio (o/e) 0.76, 90% interval 0.37 to 1.63. That is too few expected variants to judge how well the gene tolerates losing a copy. Missense variants: 144 observed, 139.1 expected, observed/expected ratio (o/e) 1.04, 90% interval 0.9 to 1.19. Synonymous variants: 61 observed, 52.98 expected, observed/expected ratio (o/e) 1.15, 90% interval 0.94 to 1.42.
Homologues: Orthologues: macaque LCE1F (90% identical). Paralogues in human: LCE1F (94% identical), LCE1D (91% identical), LCE2D (70% identical), LCE2A (69% identical), LCE2C (69% identical), LCE2B (69% identical), LCE5A (68% identical), LCE3C (49% identical), LCE3B (48% identical), LCE3D (47% identical), LCE3A (47% identical), LCE3E (47% identical), and 8 more.